U8 (U8 small nucleolar RNA )
Synonyms: LOC124900319
Gene: Small nucleolar RNA gene on chromosome 12 (73,764,279 to 73,764,413, reverse strand). Ensembl gene ENSG00000201809.
Gene Ontology:
Biological process: RNA processing
Cellular component: nucleolus
Homologues: Orthologues: chimpanzee U8 (99% identical), pig U8 (72% identical), dog U8 (71% identical). Paralogues in human: U8 (79% identical), U8 (77% identical), U8 (76% identical), U8 (73% identical), U8 (72% identical), U8 (71% identical), U8 (70% identical), U8 (69% identical), U8 (59% identical), U8 (46% identical).